CYP17A1 (cytochrome P450 family 17 subfamily A member 1)
Diseases named in the same sentence as CYP17A1 in open-access papers (continued):
Sharing a sentence is not in itself a finding about the gene and the disease.
polycystic ovary syndrome (31 papers, 2013 to 2025). A disorder that manifests as multiple cysts on the ovaries. "In Pakistani women, there was a substantial correlation between the risk of infertility in polycystic ovary syndrome and the occurrence of the CYP17A1 polymorphism." (PMID 35205347, 2022). "In a 2015 case–control study of Iraqi women, two groups of individuals were examined for genetic association between the CYP17A1 allele and the incidence of polycystic ovary syndrome." (PMID 35205347, 2022). "This can be explained by theca cell defect in polycystic ovaries causing over expression of steroidogenic enzymes particularly CYP17A1 enzyme that enhances DHEA production." (PMID 34932604, 2021). "For example, elevated ovarian expression of CYP17A1 has been associated with increase androgen and metabolic disturbances in polycystic ovary syndrome (PCOS), which contributes to hyperandrogenism, disrupted folliculogenesis, and increased risk of infertility." (PMID 40451068, 2025). "In bovine ovarian stromal cells, the activation of p38 and JNK is involved in regulating the expression of CYP17A1 and PAI-1, both of which are associated with hyperandrogenemia and ovarian fibrosis in PCOS." (PMID 40660328, 2025). "And previous studies suggested that an upregulation of CYP17A1 expression underscore pivotal roles in the pathogenesis of polycystic ovary syndrome." (PMID 40370520, 2025). "Our in vivo study revealed that the ferroptosis inducer, RSL3, induced polycystic ovaries and that hyperandrogenism with CYP17a1 increased in rats." (PMID 38550897, 2024). "Polycystic ovary syndrome (PCOS) has been linked to aberrant folliculogenesis and abnormalities in the aromatase enzyme (Cyp19a1) and the steroidogenic enzyme, 17-alpha-hydroxylase (Cyp17a1) expression." (PMID 36297046, 2022). "Also, clinical investigations point to dysregulation of Klf4 and Cyp17A1 expression in the ovaries of patients with polycystic ovary syndrome (PCOS)." (PMID 38255178, 2023). "In addition, increased expression of LHCGR and CYP17A1 in human polycystic ovaries’ theca cells has been observed." (PMID 30944702, 2019). "CYP17A1 is overexpressed in theca cells of women with PCOS, and its overexpression is driven by increased insulin receptor signaling, such that hyperinsulinemia can eventually cause hyperandrogenemia." (PMID 24717046, 2014). "In addition to genotyping, TC was reported as the mutant allele and TT as the wild allele; nevertheless, the genotyping investigation did not reveal a relationship between polycystic ovarian syndrome and the CYP17A1 polymorphism." (PMID 35205347, 2022). "Jakimiuket al studied the genetic basis of receptors in granulosa and theca cells of polycystic ovaries and reported higher mRNA expression levels of LH receptor (LHR), StAR, CYP11A1, and CYP17A1." (PMID 27769286, 2016). "Furthermore, the expression levels or enzymatic activities of CYP17A1 and HSD3B1 have been related to androgen production in polycystic ovary syndrome." (PMID 27057163, 2016). "Additionally, oxidative stress appears to also induce key steroidogenic molecules in TC, namely, CYP11A1, CYP17A1, 3-β-HSD, and StAR, favoring hyperandrogenemia." (PMID 25763405, 2014).
congenital adrenal hyperplasia (28 papers, 2012 to 2026). Congenital adrenal hyperplasia (CAH) is an inherited endocrine disorder caused by a steroidogenic enzyme deficiency that is characterized by adrenal insufficiency and variable degrees of hyper or hypo androgyny manifestations, depending of the type and the severity of the disease. "17α-hydroxylase/17,20-lyase deficiency (17-OHD) is a rare form of congenital adrenal hyperplasia caused by CYP17A1 gene variants." (PMID 37316894, 2023). "17α-Hydroxylase deficiency (17OHD) is a rare form of congenital adrenal hyperplasia caused by mutations in the CYP17A1 gene." (PMID 36210947, 2022). "The mutations in the CYP17A1 gene are therefore connected with the pseudohermaphroditism, and adrenal hyperplasia." (PMID 36467577, 2022). "Here we report, supported by careful phenotyping, genotyping and functional analysis, a prismatic case series of patients with congenital adrenal hyperplasia due to 17α-hydroxylase (CYP17A1) deficiency (17OHD)." (PMID 34524979, 2021). "17α-Hydroxylase/17,20-lyase deficiency (17OHD) caused by mutations in the CYP17A1 gene is a rare form of congenital adrenal hyperplasia typically characterised by cortisol deficiency, mineralocorticoid excess and sex steroid deficiency." (PMID 34524979, 2021). "Mutations in CYP17A1 gene typically cause congenital adrenal hyperplasia and hypokalemic hypertension." (PMID 23133444, 2012). "This pathogenesis is similar to that of 17 alpha hydroxylase deficiency, which is a CYP17A1 in congenital adrenal hyperplasia (CAH), in which an upstream substrate, corticosterone, accumulates and also acts as a weak glucocorticoid and, sometimes, at very high levels, suppresses ACTH." (PMID 40136360, 2025). "17-OHD is a rare form of congenital adrenal hyperplasia caused by mutations in the CYP17A1 gene." (PMID 28008861, 2017). "17α-hydroxylase/17,20-lyase deficiency (17-OHD) is a rare autosomal recessive disorder caused by variants in the CYP17A1 gene, accounting for approximately 1% of congenital adrenal hyperplasia (CAH) cases." (PMID 41220582, 2025). "17α Hydroxylase/17–20 lyase deficiency (17OHD) is a rare autosomal recessive form of congenital adrenal hyperplasia (CAH) caused by biallelic mutations in the CYP17A1 gene, encoding cytochrome p450c17." (PMID 39020240, 2024). "17-alpha-hydroxylase deficiency (17OHD) is a rare autosomal recessive disorder caused by mutations in the CYP17A1 gene, with an estimated incidence of 1 in 50 000, accounting for only 1% of congenital adrenal hyperplasia (CAH)." (PMID 37199305, 2023). "Mutations affecting CYP17A1 function are reported to cause congenital adrenal hyperplasia (CAH), a rare inherited disorder that affects both sexes." (PMID 32472014, 2020). "Through CYP17A1 inhibition, however, abiraterone acetate can cause cortisol deficiency with a state of excess of mineralocorticoids in a similar manner to 17-alpha hydroxylase deficiency in congenital adrenal hyperplasia (CAH)." (PMID 40136360, 2025). "Congenital adrenal hyperplasia (CAH) refers to a group of seven monogenic adrenal disorders, caused by pathological variants in genes coding for enzymes in the adrenal steroidogenic pathway: CYP21A2, CYP11B1, CYP17A1, HSD3B2, STAR, CYP11A1, and POR." (PMID 41450580, 2025). "Congenital adrenal hyperplasia (CAH) is a group of autosomal recessive disorders caused by pathogenic variants identified in seven genes (CYP21A2, CYP11B1, CYP17A1, HSD3B2, StAR, POR, and CYP11A1) involved in the steroidogenesis pathway." (PMID 39451515, 2024). "Congenital adrenal hyperplasia (CYP21A2, CYP11B1, HSD3B2, CYP17A1, POR defects) constitutes the largest subgroup of impaired steroidogenesis and represents the most common cause of PAI in children." (PMID 27485500, 2016).
hyperandrogenism (26 papers, 2009 to 2026). Excessive secretion of androgens from the adrenal glands or gonads. "The decreased DHEAS and A4 levels together with the inhibition of the 17,20 lyase activity of CYP17A1, may impact production of androgens in clinical conditions associated with androgen excess." (PMID 31031706, 2019). "In Lrp2high TC, Cyp17a1 and Hsd3b1 are predominantly expressed, with Cyp17a1 showing particularly high levels, emphasizing this subpopulation’s role in androgen excess in PCOS." (PMID 40831751, 2025). "Females with active CS typically experience hyperandrogenism as a result of stimulated adrenal androgen production, which can be suppressed by ketoconazole, an inhibitor of CYP17A1, and other enzymes in the androgen synthesis pathway." (PMID 33216275, 2021). "Furthermore, via reducing insulin-mediated CYP17A1 activation in theca cells, overall improvements in insulin sensitivity directly alleviate ovarian androgen excess." (PMID 41596408, 2026). "Clinical studies suggest that enhanced CYP17A1 enzyme activity and expression may account for hyperandrogenism in PCOS." (PMID 35992123, 2022). "In fact in the case of affected with PCOS, a potential for up-regulation of CYP17A1 expression in AT was proposed that may contribute to hyperandrogenism." (PMID 34233642, 2021). "Because hyperandrogenism is a major pathophysiological feature of PCOS, we examined the excessive androgen generation resulting from hormone imbalances and CYP17A1 and HSD3B2 activity—key enzymes involved in steroidogenesis." (PMID 29757997, 2018). "Previous studies showed that in PCOS theca cells the expression and activity of the P450c17 and 3β-HSD is elevated, and the CYP17A1 promoter activity is also increased, which partly participated in hyperandrogenism of PCOS." (PMID 23421880, 2013). "SET played a positive role in regulating ovarian testosterone biosynthesis by enhancing the transcription of steroidogenic enzymes CYP17A1 and HSD3B2, which maybe contribute to the hyperandrogenism in PCOS." (PMID 23421880, 2013). "SET played a positive role in regulating ovarian androgen biosynthesis by enhancing the transcription of steroidogenic enzymes CYP17A1 and HSD3B2, which maybe contribute to the hyperandrogenism in PCOS." (PMID 23421880, 2013). "The network pharmacology analysis report found 988 PCOS-related genes, 108 hyperandrogenism-related genes, and 377 oligomenorrhea-related genes, and we finally shortlisted 5 common genes in PCOS, hyperandrogenism, and “oligomenorrhea”: NR3C1, PPARG, FOS, CYP17A1, and H6PD." (PMID 39294254, 2024).
Infertility (17 papers, 2014 to 2025). "Both in XX and XY mice, depletion for CYP17A1 exclusively causes phenotypically female appearance (external genital phenotype), abnormal inner genitalia development and infertile phenotypes." (PMID 38451917, 2024). "Standardized treatment with dexamethasone and frozen-thawed embryo transfer with an artificial cycle protocol of endometrium preparation should be the choice for infertile female patients with CYP17A1 deficiency." (PMID 37542252, 2023). "We report a full-term live singleton birth from a woman with partial 17α-hydroxylase/17,20-lyase deficiency who presented with secondary amenorrhea and infertility caused by compound heterozygous CYP17A1 mutations." (PMID 37542252, 2023). "Here, we study the incidence of polymorphisms in the CYP17A1 gene that causes robust PCOS risk with infertility." (PMID 35205347, 2022). "Similarly, cyp17a1-/- XX and XY Nile tilapia undergo complete spermatogenesis but are infertile due to 11 keto-testosterone deficiency." (PMID 40857739, 2025). "Interestingly, a CpG-SNP in the promoter of CYP17A1 is associated with Oligoasthenoteratozoospermia and testosterone levels in infertile males and the degree of methylation in the SNP site was high in colon and stomach tissue while low in testis, kidney and adrenal gland." (PMID 25375650, 2014). "Lycium barbarum caused an up-regulation in the expression of CYP19A1, CYP17A1, AR, and SRD5A2, which in turn increased the level of serum testosterone to combat infertility." (PMID 40149961, 2025). "We evaluated the occurrence of polymorphisms in various ethnicities in the CYP11A1, CYP17A1, and CYP19A1 genes and their efficacy on increasing PCOS risk with infertility." (PMID 35205347, 2022). "We have chosen the genetic polymorphism of the genes involved in the steroidogenesis pathway as the candidate genetic variants that are susceptible to infertility between females with PCOS, focusing on CYP11A1, CYP17A1, and CYP19A1." (PMID 35205347, 2022). "Because each individual’s SNP profile is unique, more investigations in various populations are required to resolve the controversy surrounding the effect of CYP11A1, CYP17A1, and CYP19A1 polymorphisms on infertility and PCOS." (PMID 35205347, 2022). "The cyp17a1 gene was upregulated in 5-aza-dC-treated lymphocytes of infertile men, but it was downregulated in our study." (PMID 29216900, 2017). "In conclusion, our study strongly suggests that the CYP11A1, CYP17A1, and CYP19A1 genes might significantly enhance the probability of developing PCOS with infertility." (PMID 35205347, 2022).
Insulin resistance (14 papers, 2016 to 2025). Increased resistance towards insulin, that is, diminished effectiveness of insulin in reducing blood glucose levels. "Because CYP17A1 is involved in steroidogenesis and earlier studies have shown that changes in sex hormones are associated with insulin resistance, we conducted a series of assays to investigate the effect of its deficiency on metabolic syndrome." (PMID 41385510, 2025). "As previous studies suggest that insulin resistance is caused by VAT dysfunction, it is assumed that the metabolic shift induced by Cyp17a1 deletion protects against metabolic disorders despite obesity." (PMID 41385510, 2025). "In consistent with cellular results, CYP17A1 knockout mice, apparent impaired glucose tolerance, insulin resistance, corresponding changes in the levels of hormones, accelerated vascular endothelial injury and promoted formation of atherosclerosis." (PMID 37370070, 2023). "To achieve this, we produced Cyp17a1 KO rats and verified their obesity phenotype, assessing key components of metabolic syndrome including blood glucose levels, blood pressure, glucose tolerance, and insulin resistance." (PMID 41385510, 2025). "In cell models, CYP17A1 was found to be involved in glucose metabolism by increasing glucose intake and utilization, through activating IGF1/mTOR/HIF1-α signaling way, which was consistent in CYP17A1 knockout mice with impaired glucose tolerance and insulin resistance." (PMID 37370070, 2023). "This suggests that deletion of the Cyp17a1 gene may suppress insulin resistance, but further research involving a comprehensive analysis of glucose-lipid metabolism including skeletal muscle and liver is necessary to confirm the effectiveness of the Cyp17a1 KO model." (PMID 41385510, 2025). "The CYP17A1 gene may affect PCOS pathogenesis via the impact on serum testosterone levels and homeostatic model assessment for insulin resistance (HOMA-IR)." (PMID 30944702, 2019). "Since the synthesis of glucocorticoids and sex hormones depends on the CYP17A1 involved in steroidogenesis, the disruption of hormone secretion in our Cyp17a1 KO rats may contribute to their metabolically healthy obesity phenotype without insulin resistance." (PMID 41385510, 2025).
adenoma (12 papers, 2016 to 2025). A neoplasm arising from the epithelium. "CYP11B, KCNJ5, VSNL1, CYP17A1 and Ki67 were detected by immunohistochemistry on formalin‐fixed paraffin‐embedded adrenal tissue (normal; n=2, adenoma; n=11, adenocarcinoma; n=7)." (PMID 36214464, 2022). "CYP11B (215,) had significantly higher expression than CYP17A1 (72.5,) in adenomas (p=0.004) and carcinomas (p=0.016)." (PMID 36214464, 2022). "Our result showed no immunoreactivity of CYP11B1 and weak immunoreactivity of CYP17A1 presented in this KCNJ5 157-159delITE mutated adenoma." (PMID 34440230, 2021). "The mRNA levels of steroidogenic enzymes (including CYP11B1 and CYP17A1) were high in the right adenoma, whereas CYP11B2 was highly expressed in the left adenoma." (PMID 36960396, 2023). "The ratio of CYP17A1 to HSD3B2 mRNA expression levels has been related to several endocrine diseases with a low level in APAs and high level in cortisol-producing adenomas." (PMID 27057163, 2016). "The immunoreactivity of CYP17A1 in that adenoma did not increase when compared to adjacent normal-looking adrenal tissues." (PMID 34440230, 2021). "The CYP11B2 (aldosterone synthase) and CYP17A1 mRNA expressions were significantly higher in both the A/CPA and pure APA tumors than in the normal adrenal cortex, indicating that the excess aldosterone and cortisol did come from the adenomas in these patients." (PMID 29770148, 2018). "For other steroidogenesis related enzymes, such as 3β-Hydroxysteroid dehydrogenase (HSD3B), 17α-hydroxylase (CYP17A1), and 11β-hydroxylase (CYP11B1), their IHC staining was not enhanced in the adenoma, but was observed in the adjacent adrenal gland tissues." (PMID 34572956, 2021). "CYP11B1 and CYP17A1 were highly expressed in the right adenoma and CPAs, whereas CYP11B2 was highly expressed in the left adenoma and APAs compared with other adrenal diseases and nonfunctional adenoma." (PMID 36960396, 2023). "In contrast, tumors that are composed predominantly of ZG-like compact cells are typically enriched in ATP1A1-, ATP2B3-, and CACNA1D-mutant aldosterone-producing adenomas that show increased and strong CYP11B2 expression and predominantly negative CYP11B1 or CYP17A1 expression profiles." (PMID 29594118, 2018).